MET (MET proto-oncogene, receptor tyrosine kinase)
Diseases named in the same sentence as MET in open-access papers (continued):
Sharing a sentence is not in itself a finding about the gene and the disease.
lung cancer (continued). "In addition, mutations of the MET gene, within the same RON RTK family, were also found in brain metastases and correlated with resistance to radiation therapy in lung cancer." (PMID 35454943, 2022). "Aberrant activation of MET signaling pathway may contribute to the tumorigenesis process of lung cancer." (PMID 36619616, 2022). "KRAS mutation subtypes such as G12D and comutations such as CDKN2/A and MET may modulate the immunotherapy responses and outcome in lung cancer." (PMID 36230855, 2022). "c-MET is a receptor tyrosine kinase abnormally activated in many cancer types, such as renal, liver, head and neck, gastroesophageal, breast, and lung cancer, and activates several intracellular signaling pathways including RAS-MAPK, PI3K-AKT, RAC1, and PAK to promote the progression of cancers." (PMID 35558557, 2022). "These cancer progression and autophagy regulation of FAM83A-AS1 may be via MET-AMPKɑ signaling, which can lead to potential targeting for lung cancer therapy." (PMID 35635086, 2022). "Mutations in lung cancer driver genes (KRAS, EGFR, BRAF, ALK, ROS1, MET, RET, and ERBB2) in the high- and low-risk groups were shown on a waterfall plot, which demonstrated that the low-risk group (20%) harbored a higher EGFR mutation frequency than did the high-risk group (8%)." (PMID 36353226, 2022). "One of the standards of treatment in lung cancer is targeting MET alterations." (PMID 36551663, 2022). "Finally, we identified two lung cancer patients with MET+ and NTRK1+ tumors, respectively, who responded well to crizotinib treatment." (PMID 36369474, 2022). "MiR-22-3p suppressed cell growth via MET/STAT3 signaling in lung cancer." (PMID 36276078, 2022). "Taking together, FAM83A-AS1 regulates cancer progression and autophagy may via MET-AMPKα signaling in lung cancer." (PMID 35635086, 2022). "We hypothesized that FAM83A-AS1 functions in lung cancer cells may be through MET-AMPKα signaling and tested the hypothesis by more in-depth experiments." (PMID 35635086, 2022). "Intriguingly, in EGFR-mutant HCC827 lung cancer cells subjected to prolonged gefitinib treatment in tissue culture, an acquired resistance mechanism involved MET gene amplification, Met-dependent HER3–tyrosine phosphorylation, and HER3-dependent activation of PI3K downstream of Met." (PMID 35249128, 2022). "MET expression was correlated with increased migration and invasion of lung cancer cells." (PMID 34527665, 2021). "Ongoing clinical trials assessing the efficacy of MET inhibitors in lung cancer." (PMID 34722241, 2021). "Hence, genistein inhibits the proliferation of lung cancer cells by regulating the miR-27 and MET signaling pathways." (PMID 34209224, 2021). "Moreover, treatment of lung cancer cells with TKIs targeting MET (proto-oncogene) or EGFR gene alterations can instruct the TME to sustain an adaptive resistance to targeted therapies by increasing lactate release." (PMID 33673405, 2021). "In a large study of 1,387 lung cancer cases, the expression of PDL1 was reportedly high in 49% of MET mutated cases (compared to 29% of MET wild type), while tumor mutation burden was significantly lower in MET mutated cancers compared to wild-type tumors." (PMID 34425853, 2021). "Interestingly, we found increased mRNA of ROS1 and MET in ALK-positive lung cancer, the molecular mechanism is unclear at present." (PMID 34234236, 2021). "MET/EGFR signaling modulates cell proliferation in lung cancer." (PMID 31918742, 2020). "Moreover, in lung cancer, EGFR and MET mutations, oncogene fusions or STK11 inactivating mutations were associated with low response rates." (PMID 32708698, 2020). "When using thinner sections, some patients may be denied of the opportunity for targeted therapy, for instance, trastuzumab for HER2 positive breast cancer and gastric cancer, and crizotinib for MET positive lung cancer." (PMID 31101839, 2019). "In lung cancer, patients with MET exon 14 skipping responded to MET inhibitors." (PMID 31557260, 2019).
lung cancer (continued). "The frequency of MET amplification is around 1–11%, but could reach to higher level in lung cancers when acquired resistance to EGFR TKI or distal metastasis occurs." (PMID 31369639, 2019). "We measured the percentage of viable cells after 72 h exposure to those compounds with high inhibitory activity against MET gene amplified lung cancer cells EBC-1 (3d, 7a, 8a, 8b and 12c) at 25 μM, and the testing was repeated twice to determine the IC50 values in these four cancer cell lines." (PMID 31137515, 2019). "The MET signaling pathway is often dysregulated in solid malignancies, including lung cancer, as a result of several mechanisms such as autocrine/paracrine stimulation, MET overexpression, genomic amplification, translocations, point mutations and alternative splicing." (PMID 30941314, 2019). "Moreover, the spliced RNA surrogate signatures of platelets were also found to be associated with the tumor tissue molecular subtype, such as EGFR and KRAS mutations in lung cancer and HER2 and MET amplifications in BC with 85–95% accuracy rates, respectively." (PMID 31705785, 2019). "MET amplification in the 196 lung cancer samples was analyzed using tissue microarray." (PMID 31369639, 2019). "In addition, only a few studies have investigated the expression of phosphorylated MET in lung cancer." (PMID 31611604, 2019). "Because autocrine HGF-MET signaling has been previously shown to play a critical role in lung cancer progression and co-overexpression of HGF with MET is not uncommon, it is attractive to propose targeting HGF-MET also as a potential strategy to curb resistance to EGFR-TKIs." (PMID 31815659, 2019). "Activation of alternate SEMA3C‐driven RTKs may confer escape mechanisms for acquired resistance to RTK inhibitors such as ErbB2 amplification in breast cancer and MET amplification in colon and lung cancer." (PMID 29348142, 2018). "Modeling of amplification by overexpression of wild-type RET sequence validates that RET overexpression, similar to RET fusions, can lead to aberrant downstream signaling like other RTKs such as ERBB2 amplification in breast cancer or MET amplification in lung cancer." (PMID 30446652, 2018). "In this study, we found that CSE and its carcinogen B[α]P may render wtEGFR‐expressing lung cancer cells more insensitive to EGFR TKI through activation of the c‐MET/Akt signaling axis." (PMID 29570930, 2018). "We also assessed whether c-MET variation detected by the three methods was related to prognosis in lung cancer patients." (PMID 29416799, 2018). "Because larger mutation screenings—including RAS, BRAF, MET (mutations, amplifications), ERBB2 (mutations, amplifications), ALK (mutations) and ROS (mutations)—were shown to be useful in the management of lung cancer patients, targeted NGS is progressively replacing single gene testing methods." (PMID 29890761, 2018). "In addition, greater understanding of the functional activation of MET and impact of genomic aberrations will be important in understanding why selected MET inhibitors fail or succeed in lung cancer and other tumor types reliant on MET-mediated signaling." (PMID 29050231, 2017). "Thus, one approach to optimize the anticancer activity and to prevent the growth of resistant clones in MET-amplified lung cancer cells is the combined therapy with MET and EGFR inhibitors." (PMID 28968967, 2017). "HGF treatment in lung cancer cells induced cisplatin resistance via c-MET activation." (PMID 29291022, 2017). "However, lung cancer cells with amplified MET and overexpressed EGFR frequently show limited response to combined treatment, underscoring the necessity to identify additional mechanism of resistance." (PMID 28968967, 2017). "What is the implication of our findings on the potential role of MET inhibition in lung cancer?" (PMID 28141869, 2017). "In addition, activation of MET has been observed in response to treatment with EGFR TKIs in lung cancers and anti-EGFR antibodies in colorectal cancers." (PMID 28418880, 2017).
lung cancer (continued). "Collectively, our experimental data may provide a strategy for targeting the miR-329/MET interaction in a novel therapeutic application to treat lung cancer patients." (PMID 26909600, 2016). "Strikingly, NSCLC patients harboring these genetic alterations have shown remarkable responses to MET inhibitor (crizotinib or cabozantinib) in several independent early-phase trials, suggesting that MET might be a novel druggable target in lung cancers." (PMID 27223439, 2016). "We further demonstrated that miR-206 directly target MET in lung cancer A549 cells." (PMID 27014910, 2016). "Combined use of EGFR-TKI and MET inhibitors or inhibition of downstream signaling molecules might be a better second or third line choice for a group of patients with advanced lung cancer harboring wild-type EGFR." (PMID 26919104, 2016). "In addition, our results in clinical lung cancer tissue samples show that the decreased expression of miR-206 closely correlated with increased MET expression and poor cisplatin sensitivity." (PMID 27014910, 2016). "However, lung cancer cells can also become resistant by constitutive activation of parallel pathways exemplified by MET amplification." (PMID 27929064, 2016). "We next examined the potential tumorigenicity of MET in lung cancer." (PMID 26909600, 2016). "Since c-Met is the target protein of an important proto-oncogene MET, aberrations of its protein might contribute to human lung cancer." (PMID 26909600, 2016). "Expression of the oncogene hepatocyte growth factor receptor (also called MET) and its phosphorylation was associated with resistance to tyrosine kinase inhibitors used in therapy targeting EGFR in patients with lung carcinomas." (PMID 26646588, 2016). "The growth-inhibition role of miR-206 may attribute to that miR-206 targets 3′-UTR of MET mRNA, and inhibits the expression of MET in lung cancer cells." (PMID 26325180, 2015). "In order to confirm that the induction of autophagy by crizotinib in lung cancer cells was the result of MET inhibition, we used small-interference RNA to specifically target MET, and revealed that knockdown of MET mRNA resulted in the downregulation of MET expression." (PMID 26384345, 2015). "Furthermore, aberrant MET signaling activation has been identified as a prognostic factor of poor outcome in different solid tumors and also in lung cancers." (PMID 26325180, 2015). "MET is a receptor for hepatocyte growth factor and a tyrosine kinase (receptor-type tyrosine kinase), and supports the initial steps of invasion and metastasis of most human cancers, including lung cancer." (PMID 26325180, 2015). "Although the EGF receptor tyrosine kinase inhibitors (EGFR-TKI) gefitinib have shown dramatic effects against EGFR mutant lung cancer, patients become resistant by various mechanisms, including gatekeeper EGFR-T790M mutation, MET amplification, and KRAS mutation, thereafter relapsing." (PMID 24939055, 2014). "For example, EGFR-TKI resistance could be caused by MET amplification, HGF-triggered MET activation, Gas6-triggered AXL activation, and HER2 amplification in EGFR mutant lung cancer." (PMID 24952482, 2014). "The co-activation of RTKs and SFKs observed in clusters containing EGFR and MET suggested the hypothesis that functional synergy between two or more tyrosine kinases plays a role in lung cancer development." (PMID 23300999, 2013). "Therefore, we tested LMH 87 for its ability to down-regulate c-MET in A549 lung cancer cells by treating them with antibody for 8 or 24 h." (PMID 22511956, 2012). "For example, adding a MET inhibitor may be beneficial to EGFR mutant lung cancer patients whose tumors harbor MET amplification as a mechanism of EGFR TKI resistance." (PMID 22970367, 2012). "MET protein is a TK that is over expressed in various types of cancer cells, including lung cancer." (PMID 22489192, 2012). "We first examined the phosphorylation of RTKs in lung cancer cells positive for MET amplification." (PMID 21847121, 2011).
lung cancer (continued). "Our data suggest that heterodimers of MET with EGFR, HER2, HER3, or RET have differential roles in tumour development, and they provide new insight into the function of trans-phosphorylated RTKs as heterodimerisation partners of MET in lung cancer with MET amplification." (PMID 21847121, 2011). "Interestingly, the down-regulation of miR-1, which targets MET, was observed in our study, similar to previous studies in lung cancer and human Rhabdomyosarcoma." (PMID 22140553, 2011). "Molecularly targeted agents, such as epidermal growth factor receptor (EGFR)–tyrosine kinase inhibitors (TKIs), have been found to provide substantial clinical benefit in lung cancer patients, and MET is considered a molecular target of potential relevance to lung cancer." (PMID 21847121, 2011). "We thus hypothesize that c-CBL mutations might contribute to the oncogenic potential of MET and EGFR in lung cancer." (PMID 20126411, 2010). "Since East Asians with lung cancer have a higher frequency of EGFR and MET mutations in lung tumors, we also determined mutations in EGFR and MET in the same Taiwanese cohort samples and compared the results with the observed c-CBL alterations (LOH and/or mutations)." (PMID 20126411, 2010). "MET has recently been affirmed to be an attractive anti-neoplastic therapeutic target, including lung cancer." (PMID 19238632, 2008). "In this study, we sought to define the role of MET signalling in EGFR-TKI-resistant lung cancer." (PMID 19238632, 2008). "As T790M-EGFR may play a role in both intrinsic and acquired EGFR-TKI resistance in lung cancer, it would be useful to test concurrent combinatorial MET–EGFR inhibitors in clinical trials on lung cancer patients refractory to erlotinib/gefitinib." (PMID 19238632, 2008). "We hypothesised that MET signalling plays a key role in lung cancer oncogenic signalling and optimised therapy targeting MET would be effective as a treatment strategy in the face of EGFR-TKI resistance." (PMID 19238632, 2008). "Taken together, our study supports the hypothesis that MET may be targeted to circumvent T790M-EGFR-mediated intrinsic or acquired resistance to EGFR-TKI (erlotinib) in lung cancer." (PMID 19238632, 2008). "Finally, we included 10 well-known cancer-related genes (or their hotspot-containing exons) listed as most frequently mutated in lung cancer (BRAF,EGFR,ERBB2,HRAS,KRAS,MAP2K1,MET,NF1,NRAS, and RIT1) in the panel to serve as internal controls for highly mutated regions." (PMID 40867048, 2025). "Finally, the current bsAbs are mainly targeted at some mature targets (e.g., EGFR, PD1, etc.), and breakthroughs are urgently needed in the mining of new lung cancer-specific targets (e.g., c-MET, HER3) and TME regulation strategies (e.g., combining with anti-angiogenic drugs)." (PMID 40510353, 2025). "Using a novel cohort of in vivo PDX models of MET pathway activation with acquired resistance to osimertinib in EGFR-mutant lung cancer, we demonstrate that phospho-MET may be a clinically relevant assay to guide treatment selection with osimertinib and savolitinib combination." (PMID 38276867, 2024). "In a previous study conducted by the University of California Lung Cancer Consortium, 54.9% of patients had EGFR mutations, 32.9% of patients had KRAS mutations, 5.3% of patients had ALK fusions, and < 3% of patients had other mutations (HER2, MET, RET, ROS1, or BRAF-non-V600E)." (PMID 39009968, 2024). "Similarly, dual ALK‐MET inhibition may also overcome ALK‐positive lung cancer with MET‐driven resistance." (PMID 39184861, 2024). "In osimertinib-resistant lung cancer with T790M mutations, the most common mechanism of acquired resistance developing after treatment with first-generation EGFR TKIs, a significant reduction in the expression of multiple EGFR family proteins and MET, was observed." (PMID 39769452, 2024).
lung cancer (continued). "However, the low frequency of the genomic alterations in cell lines has also been observed in other vulnerabilities (e.g., MET mutations in lung cancer or BRCA1/2 in BC), and this fact has not impacted the clinical development of strategies against them." (PMID 33671201, 2021). "According to these findings, miR-27a could down-regulate MET and EGFR by targeting their 3′ UTRs directly or indirectly through Sprouty2; consequently, the underlying mechanism of the MET and EGFR axis regulation may emerge as new strategies in lung cancer treatment." (PMID 34830377, 2021). "In addition to codrivers in NSCLC, MET mutations are generally thought to be mutually exclusive with mutations in other major lung cancer drivers and have not been shown to be associated with acquired resistance to EGFR-TKI therapy." (PMID 34205733, 2021). "Our data suggest that single EGFR or MET inhibition might not be a good therapeutic option for EGFR-mutated lung cancer with MET amplification, and that inhibition of both pathways should be the best clinical choice in these patients." (PMID 34298655, 2021). "Our findings reveal that a subset of EGFR-mutant, MET-amplified lung cancers develop dependence on MET activation alone, suggesting that such patients could be treated with a single-agent MET TKI rather than the current standard-of-care EGFR and MET inhibitor combination regimens." (PMID 34516823, 2021). "Therefore, EGFR and MET can be attractive targets for lung cancer." (PMID 32070026, 2020). "Moreover, MET expression was confirmed in CTCs isolated from a lung cancer patient." (PMID 32486306, 2020). "Thus, the dual targeting of EGFR and MET might be a promising therapeutic strategy to overcome lung cancer that is sensitive or resistant to TKI." (PMID 32070026, 2020). "Interrogation of the predicted TK-substrate network generated biologically meaningful hypotheses, followed by experimental validations illustrating the effectiveness of predicted kinase inhibitor combination, EGFR and c-MET combination inhibitors, in treating lung cancer cell lines." (PMID 30615629, 2019). "Hence, although the juxtamembrane mutations of MET do not affect its known proteolytic cleavages, the R970C MET variant favors calpain dependent proteolytic cleavage in lung cancer cells." (PMID 28061464, 2017). "Activation of the HGF/c-MET signaling pathway contributes to the promotion of tumor cell motility, scattering, invasion, and metastasis, suggesting it to be a negative prognostic indicator for cell survival and recurrence in some solid tumors including lung cancer." (PMID 29069748, 2017). "Moreover, HGF increases cisplatin resistance via activation of MET in lung cancer cells." (PMID 27014910, 2016). "In contrast to patients with MET exon 14 skipping, patients with MET copy number gain were more prone to have late stage disease, poor differentiation, and acinar/solid/invasive mucinous adenocarcinoma, indicating that MET copy number gain is a late event in lung cancer." (PMID 27223439, 2016). "Furthermore, we found that MET is the direct target of miR-206 in lung cancer cells." (PMID 27014910, 2016). "Since c-Met is the target protein of an important proto-oncogene MET, Bcl2 plays anti-apoptosis role in vivo and vitro, and cyclin D1 is the key role on regulation of cell cycle regulated by MET, aberrations of these three proteins might contribute to human lung cancer." (PMID 26325180, 2015). "Therefore, a strategy by targeting G protein-coupled receptor or c-MET may reverse lung cancer cells to EGFR-TKI resistance." (PMID 26273639, 2015). "However, there are insufficient data on how MET- or AXL-mediated resistance to EGFR-TKI in lung cancer could be overcome by inhibiting HSP90." (PMID 25780909, 2015).